G3BP1 (G3BP stress granule assembly factor 1)
Description:
Protein involved in various processes, such as stress granule formation and innate immunity. Plays an essential role in stress granule formation. Stress granules are membraneless compartments that store mRNAs and proteins, such as stalled translation pre-initiation complexes, in response to stress. Promotes formation of stress granules phase-separated membraneless compartment by undergoing liquid-liquid phase separation (LLPS) upon unfolded RNA-binding: functions as a molecular switch that triggers RNA-dependent LLPS in response to a rise in intracellular free RNA concentrations. Also acts as an ATP- and magnesium-dependent helicase: unwinds DNA/DNA, RNA/DNA, and RNA/RNA substrates with comparable efficiency. Acts unidirectionally by moving in the 5' to 3' direction along the bound single-stranded DNA. Unwinds preferentially partial DNA and RNA duplexes having a 17 bp annealed portion and either a hanging 3' tail or hanging tails at both 5'- and 3'-ends. Plays an essential role in innate immunity by promoting CGAS and RIGI activity. Participates in the DNA-triggered cGAS/STING pathway by promoting the DNA binding and activation of CGAS. Triggers the condensation of cGAS, a process probably linked to the formation of membrane-less organelles. Also enhances RIGI-induced type I interferon production probably by helping RIGI at sensing pathogenic RNA. May also act as a phosphorylation-dependent sequence-specific endoribonuclease in vitro: Cleaves exclusively between cytosine and adenine and cleaves MYC mRNA preferentially at the 3'-UTR.
Synonyms: G3BP; HDH-VIII
Tractability: Small molecule: a structure with a bound ligand is known. PROTAC: UniProt records ubiquitination sites on it; ubiquitination databases record sites on it; its protein half-life has been measured.
Target class: Enzyme; Hydrolase
Gene: Protein-coding gene on chromosome 5 (151,770,951 to 151,812,911, forward strand). Ensembl gene ENSG00000145907.
Subcellular location: Cytoplasm, cytosol; Perikaryon; Cytoplasm, Stress granule; Nucleus
Subcellular location (Human Protein Atlas): Cytosol
Pathways (Reactome):
Disease: SARS-CoV-2 activates/modulates innate and adaptive immune responses
Gene Ontology:
Molecular function: ATP hydrolysis activity; DNA helicase activity; DNA/RNA helicase activity; molecular condensate scaffold activity; protein binding; ribosomal small subunit binding; RNA binding; RNA helicase activity; mRNA binding; nucleic acid binding
Biological process: defense response to virus; negative regulation of stress granule assembly; positive regulation of type I interferon production; protein deubiquitination; stress granule assembly; membraneless organelle assembly; positive regulation of stress granule assembly; Ras protein signal transduction
Cellular component: cytoplasm; cytoplasmic stress granule; cytosol; focal adhesion; nucleus; perikaryon
Genetic constraint (gnomAD): Loss-of-function variants: 13 observed, 17.8 expected, observed/expected ratio (o/e) 0.73, 90% interval 0.47 to 1.16. The upper end of that interval is the gene's LOEUF score, 1.16, which puts it in group 5 of 6, group 1 being the genes least tolerant of losing a copy. Missense variants: 224 observed, 251.16 expected, observed/expected ratio (o/e) 0.89, 90% interval 0.8 to 1. Synonymous variants: 74 observed, 83.41 expected, observed/expected ratio (o/e) 0.89, 90% interval 0.73 to 1.08.
Homologues: Orthologues: dog G3BP1 (97% identical), pig G3BP1 (97% identical), guinea pig G3BP1 (96% identical), chimpanzee G3BP1 (94% identical), mouse G3bp1 (94% identical), rat G3bp1 (94% identical), macaque G3BP1 (93% identical), tropical clawed frog g3bp1 (79% identical), zebrafish g3bp1 (70% identical), Drosophila melanogaster rin (43% identical), Caenorhabditis elegans gtbp-1 (24% identical). Paralogues in human: G3BP2 (67% identical).
Diseases named in the same sentence as G3BP1 in open-access papers:
G3BP1 is named in the same sentence as 139 diseases in open-access papers, as found by Europe PMC text mining. Sharing a sentence is not in itself a finding about the gene and the disease. The quoted sentences say what the papers report.
viral infection (68 papers, 2012 to 2026). "G3BP1 function is further modulated by post-translational modifications and also implicated in many diseases such as cancer, neurodegeneration, and viral infection—the latter is the focus of this review." (PMID 36851663, 2023). "APOBEC3B facilitates the formation of protein-RNA condensates with stress granule assembly factor (G3BP1) by protecting mRNA associated with stress granules from RNAse L-induced RNA cleavage during viral infection." (PMID 36781883, 2023). "G3BP1 potentiates the RIG-I-related pathway via RNF125-mediated K48-linked polyubiquitination in response to viral infection, which results in IRF3 phosphorylation and increased IFN-β transcription." (PMID 35652658, 2022). "To assess the impact of G3BP on the translation of viral VPg-linked RNA following viral infection, we evaluated the impact of loss of G3BP1 on the recruitment of viral RNA to polysomes under conditions where viral RNA synthesis was inhibited, namely in the presence of 2CMC." (PMID 31403400, 2019). "Several studies reported nuclear localization of G3BP1 during pathological development of disease or virus infection." (PMID 40145738, 2025). "Our findings have significantly deepened our understanding of the interactions between SARS-CoV-2 N protein and G3BP1/2, elucidating the consequences of this interplay on viral infection." (PMID 40733530, 2025). "circHOMER1 was observed to bind to G3BP1, and this interaction was also enhanced by viral infection." (PMID 40662732, 2025). "Whereas SGs are generally thought to promote antiviral responses, the specific role of G3BP1 in viral infection has been more challenging to define." (PMID 38492217, 2024). "The G3BP1 mRNA transcript level initially increased and then decreased with the progression of viral infection time, while the total amount of protein gradually decreased." (PMID 38690262, 2024). "We have shown that the severe acute respiratory syndrome coronavirus 2 (SARS-CoV-2) nucleocapsid (N) protein induces atypical N+/G3BP1+ foci (N+foci), leading to the inhibition of host immunity and facilitation of viral infection." (PMID 39459161, 2024). "Together, these results suggest that viral infection promotes TRIM25 co-condensation with G3BP1, which in turn inhibits viral infection." (PMID 38750080, 2024). "Typical G3BP1+ stress granules (tSGs) are usually formed after virus infection to restrain viral replication and stimulate innate immunity." (PMID 39459161, 2024). "To identify specific SG components that respond to viral infection, we set to characterize the G3BP1-interaction network upon poly(I:C) stimulation using a proximity-dependent biotinylation (BioID) approach." (PMID 38750080, 2024). "The N protein can engage with G3BP to suppress type I interferon (IFN) signaling and G3BP-mediated SG formation, while promoting viral infection through the neutralization of G3BP1-mediated antiviral innate immunity." (PMID 38846351, 2024). "Previous investigations into the role of G3BP1 as a regulator of viral infections have demonstrated that stress granule formation can be blocked by the binding of the viral nsP3 peptide to the NTF2L domain of G3BP1." (PMID 38284934, 2024). "Several important molecules have been shown their double-edge effects during virus infection, such as G3BP1, the core protein for stress granule, AP-1/c-Jun pathway probably has the similar effects." (PMID 38829910, 2024). "G3BP1/2 are paralogous proteins that promote stress granule formation in response to cellular stresses, including viral infection." (PMID 38492217, 2024). "Studies suggest that one of these nucleating factors, G3BP1, is necessary and sufficient for SGs to form during viral infections." (PMID 37983241, 2023). "Stress granules induced in response to viral infection can be proviral or antiviral and G3BP1 is required for SG formation." (PMID 36851680, 2023).
viral infection (continued). "Here, we performed a coimmunoprecipitation assay to examine if the SARS-CoV-2 N protein binds to PKR and G3BP1 in the context of virus infection." (PMID 37154717, 2023). "G3BP1 plays an important regulatory role in tumors, viral infection, nervous system diseases and cardiovascular diseases." (PMID 37243773, 2023). "Here, we focus on the role of G3BP1 during viral infection and the various strategies utilized by viruses to exploit or counteract G3BP1 functions." (PMID 36851663, 2023). "In this investigation, we confirmed previous reports that SARS-CoV-2 N binds to G3BP1, a key component of SGs in the context of virus infection." (PMID 37154717, 2023). "In COVID-19 patients and mice, the N protein interacts with G3BP1, suppresses SG formation, and potentiates viral infection by antagonizing the G3BP1-mediated host innate immune response pathway." (PMID 36851663, 2023). "Here, we describe the role of G3BP1 during specific viral infections and the ways by which G3BP1 is targeted." (PMID 36851663, 2023). "Similar to mammalian cells, SG formation in response to diverse stimuli such as heat shock, oxidative stress and virus infection was detected in fish cells by visualizing the formation of G3BP1 puncta suggesting conserved pathways." (PMID 36851680, 2023). "A recent study in another fish model of Grouper spleen cells infected with Red-Spotted Grouper nervous necrosis showed the requirement of G3BP1 and SG formation with an antiviral effect highlighting the diverse roles of G3BP1 and SG in viral infections." (PMID 36851680, 2023). "We performed a coimmunoprecipitation assay to examine the physical interaction between SARS-CoV-2 N and PKR/G3BP1 in the context of virus infection." (PMID 37154717, 2023). "In the case of viral infections, in G3BP1 KO cells, the replication efficiency of mammalian orthoreovirus (MRV) is significantly improved." (PMID 36937261, 2023). "SG formed during virus infection, avSG, recruit antiviral proteins and G3BP1 is required for its assembly." (PMID 36851680, 2023). "We propose that SG assembly that is known to occur through a liquid-liquid phase separation (LLPS) process is protected by A3B to promote G3BP1-RNA condensate formation when RNase L is triggered during viral infection." (PMID 36781883, 2023). "SGs are also considered to be antiviral structures when they form during viral infection, but viruses can block SG formation to facilitate their survival, often by targeting the essential SG protein G3BP1." (PMID 35085371, 2022). "SARS-CoV-2 N protein interacts with G3BP1 to inhibit host stress granule (SG) assembly and promote viral infection." (PMID 36528612, 2022). "G3BP1 is also involved in the innate immunity of cells, especially during the process of viral infection." (PMID 35935992, 2022). "At a later stage of viral infection, proteolytic cleavage of G3BP1, eIF4G, and PABP possibly releases these components from the SGs, resulting in dispersion of the SGs." (PMID 34774526, 2021). "Virus infection also results in the formation of classic TIA1/G3BP1-positive stress granules due to viral protein synthesis and replication." (PMID 33952639, 2021). "G3BP1 has also been reported to have an antiviral role during many viral infections, often activating the innate immune response through NF‐κB and Jun N-terminal protein kinase (JNK) transcription (35, 37, –, 39)." (PMID 34287041, 2021). "Responding to several types of cellular stresses, such as DNA damage, oxidative stress, and viral infection, G3BP1 is a core component of stress granules (SGs), which are critical for nucleating SG assembly." (PMID 34287041, 2021). "We further show that norovirus evades the stress granule response in a novel way by isolating and characterising the G3BP1 interactome for the first time in the context of a viral infection." (PMID 31905230, 2020).
viral infection (continued). "Vero cells were infected with IBV and at the indicated time points, cells were fixed and labelled with anti-dsRNA to detect virus infection and with anti-G3BP1 to detect SG." (PMID 32422883, 2020). "CHIKV nsP3 sequesters G3BP1/2 when expressed alone, in the context of a replicon, or during virus infection, thereby interfering with SG responses." (PMID 29875241, 2018). "That G3BP1 is central to SG dynamics is supported by the observation that G3BP1 function is often circumvented during viral infections." (PMID 26557057, 2015). "We also tested whether G3BP1 proteins altered RLR-MAVS-IRF3 signaling in response to viral infection." (PMID 38295168, 2024). "KEGG analysis is enriched in a variety of human diseases, which may be attributed to the fact that G3BP1 protein can mediate viral infection via SGs." (PMID 37904149, 2023). "G3BP1 also serves as the central hub for the protein–protein and protein–RNA interactions within a class of biomolecular condensates called stress granules (SGs) during stress conditions, including viral infection." (PMID 36851663, 2023). "Stress granules, which are largely nucleated by G3BP1, serve as hubs for mRNA triage, but there is mounting evidence that they also perform cell signaling functions that are vital to cell survival, particularly during viral infection." (PMID 35085371, 2022). "NPSARS-CoV-2 could efficiently suppress G3BP-mediated SG formation and potentiate viral infection by overcoming G3BP1-mediated antiviral innate immunity." (PMID 35652658, 2022). "Specifically, N protein interacts with G3BP1 to disrupt SG assembly during viral infection." (PMID 34774526, 2021). "Interestingly, the role of G3BP1 varies in viral infections, from limiting alphavirus replication (67, –, 69) to interacting with the HCV RdRp NS5B and enhancing the production of HCV infectious virus particles (70, –, 72)." (PMID 30944179, 2019). "Our findings add to the body of evidence supporting that targeting of the cellular protein G3BP1 can be used as an antiviral approach and validates the use of PROTACs for the efficient and specific degradation of cellular factors as a feasible methodology to combat viral diseases." (PMID 41586493, 2026). "While our data suggest that G3BP1 proteins do not generally alter innate immune signaling pathways, it remains possible that G3BP-mediated viral RNA condensation could alter the activation of these pathways via yet-to-be determined mechanisms during specific viral infections." (PMID 38295168, 2024). "Importantly, the capability of G3BP1 to promote SG assembly is not limited to cases of viral infection, and this protein is considered one of the key regulators of the SG biogenesis, promoting assembly of these MLOs in response to various environmental stresses." (PMID 36768473, 2023). "VHSV induces SG formation and in the early stages it may be used to produce IFN and as viral infection proceeds the expression of viral proteins and the redistribution of SG protein, G3BP1, for effective viral mRNA translation may tip the translation in favor of viral proteins." (PMID 36851680, 2023). "However, the relationship between red-spotted grouper nervous necrosis virus (RGNNV) infection and SGs, and the roles of the SG marker protein RAS GTPase-activating protein (SH3 domain)-binding protein 1 (G3BP1) in viral infection remain unclear." (PMID 35935992, 2022). "Additionally, an immunoprecipitation assay performed for G3BP1 during RFP-tagged ORF120 revertant virus infection also showed that G3BP1 could interact with RFP-tagged ORF120 revertant virus using anti-myc or anti-RFP antibodies." (PMID 34287041, 2021). "The G3BP1-induced SGs increased rapidly and reached a peak 4 hours after SVA virus infection of apical-out porcine intestinal organoids." (PMID 40849899, 2025). "Even though viral infection results in SG formation, VHSV still influences G3BP1 to facilitate its own replication." (PMID 38543839, 2024).
viral infection (continued). "Additionally, as a nucleating protein of SGs, G3BP1 binds mRNAs, 40S ribosomal subunits, initiation factors (eIF2, eIF3, eIF4), and RNA-binding proteins (e.g., poly(A) binding protein, Caprin1) for SGs assembly and protein translation arrest after viral infection." (PMID 39638802, 2024). "However, the mechanisms by which G3BP1/2 antagonize viral infection remain unclear." (PMID 38295168, 2024). "Our data agree with a recent report showing that knocking out both G3BP1 and G3BP2 is required for SG inhibition during viral infections." (PMID 37983241, 2023). "Biochemical analysis of avSGs using purified SGs revealed interaction of G3BP1 with Rig-I and PKR, which is consistent with avSGs being assembled in response to virus infection and dsRNA (35, 36, 39, –, 41)." (PMID 32295917, 2020). "Consistently, infection with a non-G3BP-1 binding SFV promotes a persistent accumulation of SGs containing G3BP-1 and TIA-1, which correlates with an attenuation in viral infection." (PMID 31681621, 2019). "On the other hand, G3BP1 and G3BP2 had antiviral activity against poliovirus (PV) and alphaviruses, suggesting a variety of possible mechanisms of action in viral infections." (PMID 24992036, 2014). "Combined, these data indicate that components of the RLR-MAVS-IRF3 pathway do not highly enrich in G3BP1 RNP complexes (SGs/RLBs) during the innate immune response to dsRNA or viral infection." (PMID 38295168, 2024). "The global distribution of viral proteins as well as the percentage of cells expressing N and S were similar in both conditions, confirming that G3BP1/2 did not significantly impact viral infection, from virion entry to the translation of N and S proteins." (PMID 38245532, 2024). "To test whether viral infection promotes the co-localization of TRIM25 and these AVPs, we examined the subcellular localizations of G3BP1, TRIM25 and multiple AVPs in TRIM25 KO HeLa cells that were rescued with GFP-TRIM25 WT or ∆PTFG." (PMID 38750080, 2024). "RLBs are small, punctate G3BP1-positive foci that are generated independently of canonical dsRNA-induced SGs during viral infection because PKR activity is not required for RLB formation." (PMID 36781883, 2023). "Virus replication is enhanced in the absence of both TDRD3 and G3BP1, and virus infection leads to cleavage of TDRD3 by the enterovirus proteinase 2A." (PMID 35085371, 2022). "Their components, G3BP1 and G3BP2, may play important roles in viral replication and may also promote the innate immune response after viral infection of the host cell." (PMID 34526993, 2021). "Although it seems hnRNPM formed puncta structures in cytoplasm after virus infection, confocal microscopy experiments showed that hnRNPM was not co-localized with G3BP1 (as a marker of stress granules)." (PMID 31433824, 2019). "In this scenario, the G3BP1 NTF2L-derived peptide encompassing F33 might be able to restore SG assembly and cellular defense by blocking the interaction with viral proteins, indicating its therapeutic potential in viral diseases." (PMID 38731625, 2024). "Previous examples of inhibition of viral infection by targeting human proteins include for example targeting of the interaction between the ebolavirus protein VP30 and host protein PP2A-B5679, and inhibition of the interaction between N (SARS-CoV-2) and human G3BP1/217." (PMID 37100772, 2023). "Importantly, expression of G3BP1/2 was not drastically induced upon virus infection in Calu-3 cells." (PMID 36081788, 2022). "Furthermore, knock-down of other SG factors associated with virions differently impacted SARS-CoV-2 replication, suggesting that the function of G3BP1/2 in viral infection may not be directly or solely related to their role in SG assembly." (PMID 38245532, 2024).